CHRNA3 (cholinergic receptor nicotinic alpha 3 subunit)
Diseases named in the same sentence as CHRNA3 in open-access papers (continued):
Sharing a sentence is not in itself a finding about the gene and the disease.
esophageal cancer (1 paper, 2014). A primary or metastatic malignant neoplasm involving the esophagus. "It has been shown that CHRNA5 (neuronal acetylcholine receptor subunit alpha-5) and CHRNA3 (neuronal acetylcholine receptor subunit alpha-3) as negative regulators of nicotine signaling in bronchial cancer and esophageal cancer cells." (PMID 24621512, 2014). "Consistently we observed an increased growth rate for esophageal cancer cells by nicotine treatment or through knockdown of CHRNA3." (PMID 24621512, 2014). "Consistently, we observed nuclear translocation and activation of YAP1 by knockdown of CHRNA3, which is a negative regulator of nicotine signaling in bronchial and esophageal cancer cells." (PMID 24621512, 2014). "Nicotine administration or CHRNA3 depletion substantially increased proliferation and migration in esophageal cancer cells." (PMID 24621512, 2014). "In this study, we have shown that nicotine administration or CHRNA3 depletion lead to an increase of cell growth and migration, and induce resistance to apoptosis in esophageal cancer cells." (PMID 24621512, 2014).
heroin addiction (1 paper, 2024). "A haplotype block across CHRNA5, CHRNA3, and CHRNB4 was linked to changes in sexual desire post-long-term heroin use, highlighting the connection between nAChRs gene polymorphisms and heroin addiction phenotypes in the Chinese Han population." (PMID 38862938, 2024).
metastatic disease (1 paper, 2023). "In contrast, in 14/30 samples of patients with metastatic disease, PHOX2B (n = 13, 9.2 copies/mL, range 0.4–47 copies/mL) and/or CHRNA3 (n = 4, mean 5.4 copies/mL, range 2.1–11 copies/mL) was detected." (PMID 37046768, 2023).
psoriasis (1 paper, 2023). An autoimmune condition characterized by red, well-delineated plaques with silvery scales that are usually on the extensor surfaces and scalp. "In genetic analyses, the odds ratio of developing moderate to severe psoriasis was 1.05 (0.95-1.16) per CHRNA3 rs10511730 T-allele in ever smokers." (PMID 36911745, 2023).
psychosis (1 paper, 2025). "Among the 170 propsychotic target genes, 8 were a high-confidence psychosis risk gene (GRIN2A, DRD2, CYP2D6, CHRNB4, CHRM4, GABBR1, GRM3, CHRNA3)." (PMID 40701976, 2025).
thrombosis (1 paper, 2022). "The CHRNA3 locus is associated with nicotine dependence, and F5 Leyden plays a role in thrombosis, suggesting that smoking and thrombosis may play a greater role in LEAD compared to atherosclerosis in other arterial territories." (PMID 36142394, 2022).
thymoma (1 paper, 2023). A neoplasm arising from the epithelial cells of the thymus. "More recently, using microarray profiling, Guo and colleagues demonstrated lower transcriptional levels of CHRNA3 and AIRE in MG compared to non-MG thymomas." (PMID 36979710, 2023).
tongue cancer (1 paper, 2025). A malignant neoplasm affecting the tongue. "The qRT‐PCR analysis revealed that CHRNA5 expression was highest, followed by CHRNA7 and then CHRNA3, in SCC‐4 tongue cancer cells." (PMID 41201200, 2025). "We integrated analyses of SCC‐4 tongue cancer cells with CHRNA overexpression, immunohistochemistry of OSCC pathological specimens, and data from the cancer genome atlas (TCGA), DepMap, and Puram 2017 to assess CHRNA3, CHRNA5, and CHRNA7 in OSCC/HNC." (PMID 41201200, 2025).
cancer (15 papers, 2014 to 2025). A tumor composed of atypical neoplastic, often pleomorphic cells that invade other tissues. "CHRNA3 polymorphism may contribute to the cancer occurrence through two feasible mechanisms: direct or nicotine dependent cancer promotion." (PMID 26831765, 2016). "CHRNA3 was identified to increase the sensitivity of cancer cells to chemotherapeutic agents, such as chelerythrine, XK-469, and dexamethasone decad, while GABRD weakened the sensitivity of pimozide and rapamycin." (PMID 38099288, 2023). "Using Cancer Cell Line Encyclopedia, we also observed a positive correlation between the mRNA levels of CHRNA3 and insensitivity to carboplatin treatment among SCLC cell lines." (PMID 35565402, 2022). "We also found a large number of genes functioning in the plasma membrane; four genes CHRNA3, CLIC1, KCTD1 and KCNMA1 were discovered in iron channel complex; except KCTD1, all others were associated with cancer." (PMID 26367387, 2015). "For β4 nAChR, most studies have focused on the CHRNA5/CHRNA3/CHRNB4 cluster, wherein polymorphisms may be associated with an increased risk of death and incidence of cancer among smokers." (PMID 36284268, 2022). "Previous studies have determined that nicotine may promote cancer cell proliferation and metastasis through calcium channels or through CHRNA-3, 5, 7 in human PDAC." (PMID 32894161, 2020). "In our analysis, we found that seven out of 10 pedigrees had potential co-segregated pathogenic variants in known cancer-associated genes, including CHEK2, ATM, MRE11, and CTR9, and some other cancer-associated genes, such as IGF2R and CHRNA3." (PMID 31214250, 2019). "Moreover, α3-nAChR depleted cells were resistant to apoptosis-inducing agents, underscoring the importance of epigenetic silencing of the CHRNA3 gene in human cancer." (PMID 26981122, 2016). "In addition, it is through the acetylcholine receptor pathway, which was composed of CHRNA5 and CHRNA3 in the 15q25.1 locus, that nicotine promote cancer cell proliferation, survival, migration, invasion, and tumor etiology and development." (PMID 25329654, 2014). "The expression of CHRNA3, GABRD, GRIK3, and GRIK5 in cancer cells significantly impacted their response to chemotherapy." (PMID 38099288, 2023). "Our analysis of drug sensitivity revealed that the expression of CHRNA3, GABRD, GRIK3, and GRIK5 in cancer cells significantly impacted their response to chemotherapy." (PMID 38099288, 2023).
tumor (11 papers, 2012 to 2025). "The CHRNA3, GABRD, GRIK3 and GRIK5 gene are associated with the sensitivity of certain anti-tumor drugs such as fluphenazine, pimozide, isotretinoin, and fludarabine." (PMID 38099288, 2023). "Nicotine exposure alone and cisplatin treatment alone appeared to increase the mRNAs of CHRNA4, CHRNB2, and CHRNA3 in the tumor samples, while their combination resulted in further increases." (PMID 35565402, 2022). "The levels of mRNAs of CHRNA4, CHRNB2, and CHRNA3 in the tumor tissues were also quantified." (PMID 35565402, 2022). "Down-regulation of CHRNA3 expression in the two tumor types in our study could be a consequence of epigenetic silencing of this gene, which is a frequent target of aberrant DNA hypermethylation." (PMID 28978081, 2017). "Results revealed that, compared to normal tissues, the expression of CHRNA3, GRIK3, and GRIK5 is decreased in tumor tissues, while GABRD is highly expressed in tumor tissues, consistent with our bioinformatics analysis results." (PMID 38099288, 2023). "On the other hand, changes related to α3 and α5 mRNA levels found in SQC-L and ADC-L tumors in our study concur with a previous paper describing transcriptional dysregulation for CHRNA3 and CHRNA5 in lung tumor biopsies paired with their corresponding non-tumor specimens from 21 patients with ADC-L." (PMID 28978081, 2017). "In lung ADC, CHRNA3 protein was detected in tumor cells but not in stromal cells." (PMID 24686516, 2014). "This is consistent with our IHC findings, where tumor infiltrations had higher CHRNA5 levels than tumor islands, which was not the case for CHRNA3 and CHRNA7." (PMID 41201200, 2025). "The transcriptomes (scRNA‐seq) of 2215 tumor cells from 18 HNC patients were analyzed, in which CHRNA5‐dominant cells were the most (47%), followed by the cells lacking expression of CHRNA3, CHRNA5, and CHRNA7 (41%)." (PMID 41201200, 2025).
Cardiovascular disease (3 papers, 2015 to 2026). "Cardiovascular disease highlights CDKN2B-AS1, LPA, and SH2B3; respiratory system disease features CHRNA3; psychiatric disorders highlight APOE, APOC1." (PMID 41166152, 2026).
adenocarcinoma (1 paper, 2018). A common cancer characterized by the presence of malignant glandular cells. "The enrichment was stronger and more extensive in the squamous cell type, which had three loci associated with SCZ, and only one with adenocarcinoma (the CHRNA3/CHRNA5/CHRNB4 cluster on chromosome 15q25.1)." (PMID 29330379, 2018).
CHRNA3 also shares sentences with these, for which no sentence is quoted: alcohol dependence (2 papers); dependence (2); head and neck cancer (2); non-small cell lung carcinoma (2); Obesity (2); peripheral arterial disease (2); respiratory system disease (2); Abdominal obesity (1); Alcoholism (1); asthma (1); atherosclerosis (1); bipolar disorder (1); brain disorder (1); chronic bronchitis (1); Cluster headache (1); cocaine dependence (1); COVID-19 (1); diabetes (1); endometriosis (1); heart disease (1); heart failure (1); hypogonadism (1); immune system disease (1); Insulin resistance (1); ischemic heart disease (1); liver cancer (1); melanoma (1); neurological disorders (1); opioid use disorder (1); oral squamous cell carcinoma (1).
A further 4 diseases each share a sentence with CHRNA3 in 1 paper.